ENSG00000290644 (novel transcript)
Gene: Long non-coding RNA gene on chromosome 9 (92,141,298 to 92,160,114, forward strand). Ensembl gene ENSG00000290644.
Gene Ontology:
Biological process: RNA processing
Cellular component: nucleolus